INS (insulin)
Diseases named in the same sentence as INS in open-access papers (continued):
Sharing a sentence is not in itself a finding about the gene and the disease.
Hypertension (continued). "Stepwise regression indicated that no direct relationship was evident between TSI at post-conception weeks 1–12 for fasting glucose, BMI, insulin, hypertension or systolic blood pressure in adulthood." (PMID 24699387, 2014). "Genes encoding proteins that can modulate insulin signaling or action are, by definition, excellent candidates for the risk modulation of T2DM and hypertension." (PMID 24414038, 2014). "The purpose of the present study was to evaluate the association between four insulin resistance genes (ADIPOQ, LEPR, RETN, and TRIB3) and both T2DM and hypertension." (PMID 24414038, 2014). "The prevalence of hypertension and preoperative insulin use was significantly higher in the sternal wound infection group." (PMID 24885820, 2014). "Twenty-three tag SNPs in four insulin resistance genes were genotyped and analyzed for association with T2DM and hypertension." (PMID 24414038, 2014). "Thirty percentile of the people with insulin-reliant blood sugar disease and 20 percentile of the people having non-insulin reliant blood sugar mellitus develops hypertension and therefore diabetic nephropathy in later years." (PMID 28197463, 2014). "This is the first study to investigate the effects of supplementation with this combined formulation for six weeks on 24-h ABP, clinic BP and AC, blood lipids, glucose and insulin sensitivity in adults with mildly-elevated, but untreated, hypertension." (PMID 25379688, 2014). "The essential hypertensive patients with salt sensitivity are more insulin resistant than those with salt-resistance." (PMID 24485020, 2014). "Blockade of MR by spironolactone decreases local inflammation and vascular stiffness in rodent models of hypertension and insulin resistance." (PMID 24194732, 2013). "Greater percentages of patients with a history of hypertension, microvascular as well as macrovascular complications were detected in the insulin use cohort." (PMID 23308218, 2013). "The current study showed that the patients with T2DM after three months use of vitamins C, E and also combination of vitamins C and E showed significantly low level of hypertension, and improved insulin action and high level of SOD and GSH enzyme activity." (PMID 23618488, 2013). "The most common drugs that were used in T2DM patients with hypertension were amlodipine, insulin, aspirin and simvastatin." (PMID 23289895, 2013). "Second insulin has multiple actions on the sympathetic nervous system, the kidney, and the vasculature which can lead to hypertension." (PMID 23573411, 2013). "The patient was being treated with insulin (glycosylated hemoglobin [HbA1c] was 7%), and her hypertension was being controlled with an angiotensin-converting enzyme inhibitor." (PMID 23840961, 2013). "Of these female patients, 2300 were on premixed insulin only; of these on premixed insulin, 111 patients were found with proliferative retinopathy, microalbuminuria, hypertension, and hyperlipidemia." (PMID 24025198, 2013). "In obese adolescents with MS, EATT significantly correlated with metabolic and cardiac parameters such as BMI, WC, fasting insulin, IR, TG levels, hypertension, LV thickness, LVMI, MPI and carotid IMT." (PMID 24072083, 2013). "Although an insulin sensitivity enhancing effect would be expected to reduce high blood pressure, direct effects of adiponectin on components of vascular tissue are considered more important in this context." (PMID 24286214, 2013). "Correlations of BMI, WC and CI with cardiovascular risk factors (hypertension, serum LDL-C and HDL-C, glucose and insulin levels) were assessed." (PMID 23044499, 2012). "Interpretations are further complicated by seemingly contradictory effects resulting from acute and chronic caffeine treatment in some circumstances with respect to insulin sensitivity and hypertension." (PMID 24764514, 2012).
Hypertension (continued). "This generally results in an increased hepatic glucose output, decreased insulin secretion and sensitivity, central accumulation of body fat, hypertension, and an adverse lipid profile." (PMID 23259455, 2012). "While the mechanism of insulin-induced hypertension remains obscure, insulin resistance itself is known to cause diabetic dyslipidemia." (PMID 22448321, 2012). "Patients initiating exenatide b.i.d. had a statistically higher incidence of comorbidities than patients initiating insulin (P = 0.0014), i.e., a diagnosis of hypertension (69.5% vs. 65.3%, respectively) and hyperlipidemia (54.5% vs. 48.7%, respectively)." (PMID 22714818, 2012). "Aspirin was found to reduce hypertension by reduction of plasma dermcidin level, neutralized the effect of cyclooxygenase, and restored the pancreatic insulin synthesis through NO synthesis." (PMID 22448321, 2012). "More than one third of the respondents (35%, n = 145) were on insulin treatment, with 31% (n = 130) reporting high blood pressure and 18% (n = 75) reporting a history of cardiovascular disease." (PMID 22909306, 2012). "All patients 13 years and older took at least 2 prescription drugs indicated for acid reflux, allergies, anxiety, high blood pressure, cholesterol control, insulin control, and/or osteoporosis." (PMID 23226377, 2012). "Despite medication compliance and dietary control, she reported a recent history of increased insulin requirements and uncontrolled hypertension with concomitant recurrent urinary tract infections." (PMID 21226896, 2011). "For instance, myocardial glucose metabolism was increased or unchanged with insulin clamping in patients with essential hypertension, although skeletal muscle and whole-body glucose metabolism were significantly reduced with insulin clamping." (PMID 21841971, 2011). "Some even suggested a role for podiatrists in the treatment and management of hypertension and insulin dose alteration." (PMID 20051138, 2010). "For example, the annual mean treatment cost of patients on insulin is US$ 7,086 (SD ± $ 6425) and for those with hypertension the annual mean cost was 6,210 (SD ± $6,132)." (PMID 21059202, 2010). "An elevated plasma insulin plus 2 other factors-abdominal obesity, hypertension, elevated triglycerides or reduced HDL-C, and elevated plasma glucose-constituted a diagnosis of insulin-resistance syndrome." (PMID 21359028, 2010). "Early postnatal overfeeding is known to induce cardiovascular and metabolic changes such as hypertension and central obesity with increased leptin, glucose, insulin, and glucocorticoid level." (PMID 20844591, 2010). "Other parameters are the body mass index, insulin levels, arterial hypertension, glycaemia, HDL, triglycerides and microalbuminuria." (PMID 18831772, 2008). "We recommend that surgical intensive care units using labetalol infusions to control refractory hypertension have glucagon, epinephrine, insulin, phosphodiesterase inhibitors, and vasopressin readily available for administration." (PMID 18505576, 2008). "The present results show that three months of candesartan therapy improved early-phase insulin response in IGT patients with hypertension." (PMID 18633754, 2008). "In patients with essential hypertension, plasma insulin and blood glucose levels rise together, indicating reduced insulin sensitivity." (PMID 17903269, 2007). "When adiponectin was used as a dependent variable there was a significant positive relationships with 2-hr insulin values, p = 0.028 and history of hypertensions and ischemic heart disease p = 0.008 with R = 0.65." (PMID 16669997, 2006). "There was a significant positive relationships between log adiponectin and 2-hr insulin values, p = 0.028 and history of hypertensions and a ischemic heart disease p = 0.008 with R = 0.65." (PMID 16669997, 2006).
Hypertension (continued). "The role of macronutrient composition of diet on blood pressure has not been adequately studied, though any dietary intervention effective for improving insulin resistance should also have beneficial effects on hypertension." (PMID 16018812, 2005). "GLP-1RA users were younger (71.9 vs. 77.8 years, p < 0.001), had lower hypertension prevalence (61.2% vs. 78.4%, p = 0.02), and were more frequently on insulin (69.4% vs. 25.5%, p < 0.001) and sodium-glucose cotransporter 2 inhibitors (55.1% vs. 28.1%, p = 0.001)." (PMID 41745113, 2026). "Furthermore, a clinical study comparing the metabolic effects of amlodipine and sacubitril/valsartan in obese patients with hypertension reported that sacubitril/valsartan treatment improved metabolic parameters and enhanced insulin sensitivity." (PMID 41586197, 2025). "Hypertension can further damage endothelial cells, increasing insulin resistance, accelerating lipid deposition on the vessel walls, and, through the impact of high-velocity blood flow on the vascular wall, leading to vascular injury and promoting the formation and progression of arteriosclerosis." (PMID 40013309, 2025). "Dietary approaches to stop hypertension diet improved insulin sensitivity." (PMID 39857760, 2025). "However, in insulin-resistant individuals, this mechanism becomes exaggerated, leading to excessive sodium retention, increased plasma volume, and systemic hypertension." (PMID 40136609, 2025). "Similarly, hypertension exacerbates endothelial dysfunction and further impairs insulin sensitivity, while elevated HbA1c reflects poor glycemic control, a key factor in the progression of liver damage." (PMID 40520791, 2025). "A study has indicated that oxidative stress is connected with organ injury, such as left ventricular hypertrophy and carotid intima-media thickness, in children with hypertension, along with metabolic abnormalities, adipose tissue volume, and insulin resistance." (PMID 40019178, 2025). "And the 20 variables most closely associated with cardiovascular mortality were eGDR, BMI, WC, eGFR, HbA1C, SBP, age, DSP, TC, UA, TG, gender, insulin, hypertension, cholesterol-lowering medication, blood pressure medication, race, asprin, smoking status, CVD-PRS, and education level." (PMID 40756509, 2025). "Individuals with hypertension often exhibit elevated insulin levels and impaired glucose tolerance." (PMID 40725728, 2025). "For example, patients with ZD had higher rates of hypertension, neoplasms, chronic lower respiratory diseases, anemia, liver disease, nicotine dependence, malnutrition, and ischemic heart diseases, as well as more frequent use of anticoagulants and insulin." (PMID 41158645, 2025). "Second, the current model only takes blood glucose values and time as input features, failing to incorporate key clinical variables such as medication use (e.g., insulin dosage adjustments), comorbidities (e.g., hypertension, hyperlipidemia), and dietary patterns." (PMID 41452855, 2025). "The levels of total cholesterol, glycated hemoglobin (HbA1c), fasting C-peptide, fasting insulin, and prevalence of hypertension were higher, while the levels of red blood cell counts (RBC), hemoglobin, ApoA, and free triiodothyronine were lower in the ACR ≥ 30 mg/g group." (PMID 41140685, 2025). "Then, a multiple linear regression analysis was conducted, which showed that elevated plasma levels of UA, Galectin-3, and NT-proBNP, as well as age, the presence of hypertension, and the use of insulin, among others, were independently and directly related to the percentage decrease in eGFR." (PMID 40806886, 2025). "GPCRs involved in glucose and lipid metabolism, immunity regulation, insulin signaling mediation, hypertension, etc., might play a role in the pathogenesis of DN." (PMID 40422232, 2025).
Hypertension (continued). "In summary, The various metabolic disturbances observed in MetS, including dyslipidemia, hypertension, and altered glucose metabolism, can be attributed to the abnormal physiological responses driven by elevated insulin concentrations in the insulin-resistant state." (PMID 40051521, 2025). "The analysis was conducted using three models, with Model 1 being unadjusted, Model 2 adjusted for age, gender, and race, and Model 3 adjusted for multivariate variables including age, gender, race, insulin use, hypertension, total cholesterol, blood urea nitrogen, serum albumin, and smoking status." (PMID 40920656, 2025). "Patients with hypertension required higher insulin doses, likely due to their increased body mass." (PMID 40149592, 2025). "In addition, this diet improves lipid profile, enhances insulin sensitivity, and supports hypertension management through reduced sodium intake and increased potassium and fiber consumption." (PMID 40077732, 2025). "This might be comorbidities such as hypertension, chronic heart failure, and renal disease can directly affect insulin function." (PMID 39847589, 2025). "HS had higher odds of palpitations, headaches, dizziness, sleeping difficulties, brain fog, muscle weakness, joint pain, hypertension, insulin requirement, poor quality of life, and prolonged corrected QT intervals on electrocardiogram compared to NHS at two years (95% confidence interval (CI)>1)." (PMID 40084715, 2025). "Sacubitril/valsartan, used to treat hypertension and chronic heart failure, has been reported to increase urinary C-peptide levels; however, its effect on endogenous insulin secretion remains unknown." (PMID 40820210, 2025). "In addition, while eGDR serves as a practical, non-invasive marker of insulin sensitivity, it also reflects broader cardiovascular and metabolic risks, as it incorporates waist circumference, hypertension, and HbA1c." (PMID 39975601, 2025). "Additionally, DKD progressors had a higher proportion of hypertension (58.4% vs. 46.9%, P < 0.001), insulin use (43.1% vs. 31.0%, P < 0.001), and ACEI/ARB use (22.2% vs. 18.1%, P = 0.017) and a lower usage rate of SGLT2is/GLP-1RAs (8.7% vs. 11.7%, P = 0.026)." (PMID 40483478, 2025). "Additionally, they were more likely to have a history of hypertension, use antihypertensive medications, and undergo insulin therapy." (PMID 40299327, 2025). "Through processes including elevated sympathetic activity, compromised endothelial function, and activation of the renin-angiotensin-aldosterone system, IR - which is defined by the decreased cellular absorption of glucose in response to insulin - exacerbates hypertension." (PMID 40255834, 2025). "As expected, the two metabolic clusters showed very distinctive patterns in a broad spectrum of metabolic phenotypes, including age, sex, BMI, body fat percentage, waist-to-hip ratio, CRP, lipid, glucose and insulin levels, blood pressure measurements and prevalence of T2D or hypertension." (PMID 39834614, 2025). "Additionally, a randomized controlled trial involving obese patients with hypertension demonstrated that treatment with sacubitril/valsartan for 8 weeks, compared with amlodipine, improved insulin sensitivity." (PMID 39926084, 2025). "Positive correlations were observed between ACR ≥ 30 mg/g and high-density lipoprotein, fasting blood glucose, hypertension, and the ratio of 60-min postprandial insulin and serum apolipoprotein(a) (Ins60/ApoA) (r = 0.134, p = 0.001; r = 0.120, p = 0.003; r = 0.131, p = 0.001; r = 0.359, p = 0.001)." (PMID 41140685, 2025). "Additionally, CVD patients had higher rates of hypertension, greater insulin use, longer sedentary time, and higher smoking prevalence." (PMID 40920656, 2025). "In addition, gravidas with a higher degree of carbohydrate metabolism disorders requiring insulin therapy had a higher prevalence of developing genitourinary tract infections, hypertension or hypothyroidism with onset during pregnancy." (PMID 39796611, 2025).
Hypertension (continued). "High circulating levels of adiponectin have also been reported as predictors of incident cardiovascular and renal events in treated hypertensive patients and to be released upon blockade of the renin-angiotensin system in patients with essential hypertension to improve insulin sensitivity." (PMID 40272732, 2025). "Hypertension, which is defined by high blood pressure, and type 2 diabetes, a metabolic disease caused by lack of insulin and hyperglycemia, frequently coexist and work together to increase the risk of cardiovascular events, kidney damage, and death." (PMID 40859193, 2025). "For example, a 6-min walk helps in reducing central obesity by burning calories; it improves cardiovascular health and reduces vascular resistance, leading to decreased high blood pressure; it also enhances insulin sensitivity and lowers fasting glucose, which assists in lowering HbA1c." (PMID 40248408, 2025). "Similarly, structured exercise programs tailored to pregnant women have been shown to mitigate the risks of both GDM and hypertensive disorders by improving insulin sensitivity and cardiovascular function." (PMID 41488903, 2025). "In general, SNHL was associated with older age, male sex, less education, loud noise exposure, increased height/weight/waist circumference, hypertension, higher lipid levels, higher HbA1C, higher insulin dose, longer disease duration, and presence of diabetic complications." (PMID 38335215, 2024). "It was observed that speech-frequency SNHL was significantly associated with older age, male sex, less education, loud noise exposure, increased height/weight/waist circumference, hypertension, higher lipid levels, higher HbA1C, higher insulin dose, and presence of diabetic complications." (PMID 38335215, 2024). "In addition, the incidence of gestational diabetes and hypertension in the intervention group was lower than that in the control group, possibly by increasing insulin sensitivity and reducing oxidative stress." (PMID 39080659, 2024). "In these conditions insulin can affect tissues that are not directly involved in metabolism and retain insulin reactivity, thereby causing specific responses with potentially dangerous consequences including arterial hypertension." (PMID 38323106, 2024). "By enhancing insulin sensitivity, WCS may thus play a role in reducing the risks associated with hypertension." (PMID 39968409, 2024). "Notably, individuals with the highest fasting insulin and HOMA-IR levels showed a 54% and 43% increased risk, respectively, of developing hypertension." (PMID 38711979, 2024). "Approximately 50% of hypertensive patients are insulin resistant, and this defect in insulin action could contribute to the increased prevalence of both diabetic vasculopathy and hypertension." (PMID 38255878, 2024). "The sex-specific analyses results suggested direct associations between age, hypertension, alcohol intake and heavy drinking and EAT thickness in women, while inverse associations between HOMA-IR, insulin, fruit intake and EAT thickness were observed in men (Model 2)." (PMID 38796541, 2024). "However, several large-scale randomized trials examining vitamin D supplementation have reported negative outcomes, casting doubt on the potential benefits of vitamin D supplementation for hypertension, insulin sensitivity, and disturbed lipid parameters." (PMID 39498411, 2024). "Notably, insulin has the ability to activate the sympathetic nervous system and boost renal sodium reabsorption, factors known to contribute to hypertension." (PMID 39968409, 2024). "The present research indicated a nonlinear positive correlation between VAI and the prevalence of hypertension, which may be related to inflammation, insulin resistance and adipocytokine production." (PMID 38784171, 2024).